FKBP5 (FKBP prolyl isomerase 5)
Description:
Immunophilin protein with PPIase and co-chaperone activities. Component of unligated steroid receptors heterocomplexes through interaction with heat-shock protein 90 (HSP90). Plays a role in the intracellular trafficking of heterooligomeric forms of steroid hormone receptors maintaining the complex into the cytoplasm when unliganded. Acts as a regulator of Akt/AKT1 activity by promoting the interaction between Akt/AKT1 and PHLPP1, thereby enhancing dephosphorylation and subsequent activation of Akt/AKT1. Interacts with IKBKE and IKBKB which facilitates IKK complex assembly leading to increased IKBKE and IKBKB kinase activity, NF-kappa-B activation, and IFN production.
Synonyms: p54; AIG6; FKBP51; FKBP54; PPIase; Ptg-10
Tractability: Small molecule: a structure with a bound ligand is known; a high-quality ligand is known; it belongs to a druggable protein family. PROTAC: UniProt records ubiquitination sites on it; ubiquitination databases record sites on it; its protein half-life has been measured; a small molecule that binds it is known.
Target class: Enzyme
Chemical probes: SAFit1, SAfit2 (high quality)
Safety:
Unwanted effects reported when the protein is acted on. In parentheses: how it was acted on, where the effect was seen, and who reports it.
suicidal ideation (source: ClinPGx)
Gene: Protein-coding gene on chromosome 6 (35,572,945 to 35,728,622, reverse strand). Ensembl gene ENSG00000096060.
Subcellular location: Cytoplasm; Nucleus
Subcellular location (Human Protein Atlas): Nucleoplasm; Cytosol; Nucleoli fibrillar center
Pathways (Reactome):
Cellular responses to stimuli: HSP90 chaperone cycle for steroid hormone receptors (SHR) in the presence of ligand
Immune System: Modulation of host responses by IFN-stimulated genes
Signal Transduction: ESR-mediated signaling
Gene Ontology:
Molecular function: heat shock protein binding; peptidyl-prolyl cis-trans isomerase activity; protein binding; protein-macromolecule adaptor activity; FK506 binding
Biological process: negative regulation of phosphatidylinositol 3-kinase/protein kinase B signal transduction; protein folding
Cellular component: extracellular exosome; membrane; cytoplasm; cytosol; nucleus
Genetic constraint (gnomAD): Loss-of-function variants: 19 observed, 44.5 expected, observed/expected ratio (o/e) 0.43, 90% interval 0.3 to 0.63. The upper end of that interval is the gene's LOEUF score, 0.63, which puts it in group 2 of 6, group 1 being the genes least tolerant of losing a copy. Missense variants: 345 observed, 509.22 expected, observed/expected ratio (o/e) 0.68, 90% interval 0.62 to 0.74. Synonymous variants: 150 observed, 176.69 expected, observed/expected ratio (o/e) 0.85, 90% interval 0.74 to 0.97.
Homologues: Orthologues: chimpanzee FKBP5 (99% identical), macaque FKBP5 (98% identical), pig FKBP5 (96% identical), guinea pig FKBP5 (92% identical), rat Fkbp5 (91% identical), rabbit FKBP5 (90% identical), mouse Fkbp5 (87% identical), zebrafish fkbp5 (59% identical), Caenorhabditis elegans fkb-5 (11% identical), Caenorhabditis elegans fkb-4 (10% identical), Drosophila melanogaster Fkbp39 (10% identical). Paralogues in human: FKBP4 (56% identical), FKBP15 (19% identical), FKBP9 (18% identical), FKBP10 (18% identical), FKBP6 (16% identical), FKBP8 (15% identical), FKBP7 (14% identical), FKBPL (13% identical), FKBP14 (12% identical), FKBP1A (11% identical), FKBP1B (11% identical), FKBP3 (11% identical), and 6 more.
Diseases named in the same sentence as FKBP5 in open-access papers:
FKBP5 is named in the same sentence as 192 diseases in open-access papers, as found by Europe PMC text mining. Sharing a sentence is not in itself a finding about the gene and the disease. The quoted sentences say what the papers report.
depression (157 papers, 2006 to 2026). "In the present study, Fkbp5 mRNA expression was correlated with stress‐stimulated weight loss in depression model mice." (PMID 39715728, 2025). "The results of the present study show that the expressions of autophagy‐related genes (Fkbp5, Mmp9, and Map1lc3b) were increased in the hippocampus of a mouse model of depression that exhibited weight loss." (PMID 39715728, 2025). "Analyzing polymorphisms in the FKBP5 gene, another study found that the CC genotype of the rs3800373 variant is more frequent in patients with severe depression and psychosis." (PMID 40869374, 2025). "The FKBP5 gene has been shown to be closely associated with stress responses and mental health disorders, such as depression and anxiety." (PMID 40017583, 2025). "In particular, Fkbp5 mRNA expression was correlated with stress‐induced weight loss in the depression model mice." (PMID 39715728, 2025). "Electronic databases were searched up to April 11, 2023, for all literature in English and Chinese on depression, FKBP5 gene polymorphisms, and antidepressant treatment." (PMID 38609904, 2024). "Among the included studies, 12 articles investigated the association between FKBP5 gene polymorphisms and genetic susceptibility to depression." (PMID 38609904, 2024). "Recently, the immunoregulatory FKBP5 has been shown to contribute to NF-κB-driven inflammation and cardiovascular risk, and is also associated with depression susceptibility." (PMID 38433843, 2024). "Epigenetic modifications in the FKBP5 gene have been shown to be associated with early trauma, posttraumatic stress disorder, as well as depression later in life." (PMID 39257475, 2024). "It is worth noting that prior research has associated genetic variations in FKBP5 with major depressive disorder, a significant risk factor for dementia and with a higher prevalence among women." (PMID 39028752, 2024). "FKBP5 gene polymorphisms demonstrated an association with susceptibility to depression in studies conducted in Poland, Italy, Germany, the United States, and certain European countries." (PMID 38609904, 2024). "Further studies are needed to investigate a potential role of FKBP5 in the link between systemic inflammation, cardiovascular risk and depression susceptibility in psoriasis patients." (PMID 38433843, 2024). "FKBP5-associated single-nucleotide polymorphisms (SNPs), in particular rs1360780, showed an impact on depression treatment and the recurrence of depressive episodes." (PMID 38338761, 2024). "Both nucleotide and protein sequence of FKBP5 are also highly conserved across species, and a homozygous knockout of FKBP5 in mice was shown to cause abnormal depression or anxiety-related behaviours." (PMID 39702772, 2024). "Another study suggested that the FKBP5 gene’s polymorphisms contribute to the risk of depressive disorders and suicidal behavior." (PMID 38786025, 2024). "In the third study, the authors observed that patients with functional seizures, as well as patients with depression, had significantly different genotypes in FKBP5 single nucleotide polymorphisms compared with controls." (PMID 37628589, 2023). "In this investigation, the association between the six FKBP5 SNPs and the severity of depression was examined." (PMID 37051166, 2023). "In female subjects with breast cancer, certain genetic variations of FKBP5, such as rs9394309, are associated with increased fatigue, depression, and anxiety." (PMID 37398599, 2023). "Several studies have demonstrated the association of childhood trauma and epigenetic changes in FKBP5 with the development of major depression, PTSD, anxiety, and suicide." (PMID 36781843, 2023). "FKBP5 single-nucleotide polymorphisms (SNPs) have been associated with an increased risk of different psychiatric disorders (e.g., depression and post-traumatic stress disorder (PTSD)) in previous studies." (PMID 37628589, 2023).
depression (continued). "Particularly, two pairs (cg02825527–cg00130530 and cg18302629–cg00130530) were observed in three samples, and notably, cg00130530 is located at FKBP5 gene that was previously reported to be associated with suicide and depression." (PMID 36600305, 2023). "There are several polymorphisms within the FKBP5 gene which appear to moderate effects of early life stress on psychopathology, with “T” allele carriers more at risk of depression and PTSD and alterations in DNA methylation following early adversity." (PMID 39816863, 2023). "There is however evidence from studies of adults of female-specific associations between FKBP5 DNA methylation and bedtime cortisol, and between FKBP5 mRNA expression and symptoms of depression and anxiety." (PMID 39816863, 2023). "Polymorphic variants in FKBP5 have been associated with a greater risk of depression, anxiety and post-traumatic stress disorder as well as greater surgical discomfort in third molar extractions." (PMID 36834016, 2023). "FKBP5 also has a significant association with a higher probability of severe depressive disorder in subjects with methamphetamine use disorders." (PMID 37398599, 2023). "Studies aimed at uncovering gene variants involved in neuropsychiatric disorders in AD patients revealed the associations of MAOA, BDNF, TPH1, and FKBP5 genes with AD-associated depression." (PMID 35205209, 2022). "Taken together, the role of FKBP5 gene expression as causally related to depression is yet to be elucidated." (PMID 36451133, 2022). "FKBP5 single nucleotide polymorphisms (SNPs) are closely related with depression and coronary heart disease co-morbidity." (PMID 36704356, 2022). "Elevated basal FKBP5 levels in depressed patients can be a predictor of depressive disorders, while genetic polymorphisms in FKBP5 interact with early-life stress to increase the risk of developing depressive disorders." (PMID 36297314, 2022). "Given the known influence of parenting style and ELS in relation to depression, these environmental factors are of interest for investigating the possible differential susceptibility properties of FKBP5." (PMID 34423378, 2021). "Another study overviewed the association of the FKBP5 SNPs with mental health disorders and proposed four FKBP5 SNPs (rs9470080, rs1360780, rs9296158, rs3800373) are significantly associated with at least five diseases, including anxiety and depression." (PMID 34178482, 2021). "Previous research studies have evaluated genes involved in the regulation of the HPA axis to explore the genetic and functional architecture underlying HPA dysregulation in depression, such as FKBP5." (PMID 34423378, 2021). "In a European study conducted among depression treatment-resistant adolescents, FKBP5 rs1360780 was associated with suicide, a distal correlate of depression." (PMID 34765574, 2021). "This is consistent with previous reports showing increased FKBP5 methylation being associated with high levels of anxiety, depression and PTSD symptoms." (PMID 33705478, 2021). "Associations of genotype and allele of FKBP5 SNPs between cases with major depressive disorder and controls." (PMID 34516490, 2021). "A large number of studies focused their attention on the association between FKBP5 and depression or antidepressant response and Fries’s group provided a summary (Fries, Gassen & Rein, 2017)." (PMID 34178482, 2021). "Previous knowledge regarding the associations of parenting style, ELS and the FKBP5 gene on depression provides a cogent rationale for evaluating cG × E interaction effects." (PMID 34423378, 2021). "Gene association studies have shown that polymorphisms in Fkbp5 predict adult PTSD or depression onset associated with childhood traumatic stress." (PMID 33328476, 2020). "In the literature, there is some evidence for a main effect of FKBP5 polymorphisms on depression and other psychiatric disorders." (PMID 32860562, 2020).
depression (continued). "A recent meta-analysis showed that ELS interacts with an allele for FK506 binding protein 51 (FKBP5) to confer risk for depression or post-traumatic stress disorder." (PMID 31740756, 2020). "The FKBP5 protein participates in the regulation of glucocorticoid signaling and it has been implicated in various neuropsychiatric disorders including depression, bipolar disorder, and schizophrenia." (PMID 33095786, 2020). "Our finding, of carriers of the FKBP5 C allele with a more stressful CHD course displaying higher depression scores, complements the literature on the importance of FKBP5 × environment interaction." (PMID 32860562, 2020). "Considering the robust evidence regarding FKBP5 × stressor interaction on the risk for depression, we performed a linear regression model to test for possible interaction of the FKBP5 genotype and the prior CHD course on depressive symptoms." (PMID 32860562, 2020). "An increasing number of studies have investigated the association of common variants in FKBP5 and stress-related disorders like depression, posttraumatic stress disorder (PTSD), and suicidal events." (PMID 32860562, 2020). "In people with depression experiencing childhood violence, lower methylation was found for the gene encoding the FKBP5 protein, combined with a reduction of grey matter in the frontal gyrus region (on both sides)." (PMID 32373361, 2020). "As a central element of the stress system, the FKBP5 gene has been shown to be associated with depression." (PMID 32860562, 2020). "Our results point to a relevance of FKBP5 in the association of the two stress-related diseases depression and CHD." (PMID 32860562, 2020). "We further classified the CAD group into CAD+D and CAD-D groups depending on the presence of comorbid depression to investigate the association of FKBP5 gene polymorphism with susceptibility to CAD with comorbid depression." (PMID 32547886, 2020). "There is a growing body of evidence for a FKBP5 × stressor interaction to confer risk for depression, PTSD, and other psychiatric phenotypes." (PMID 32860562, 2020). "This study aimed to investigate the association of FKBP5 polymorphisms with the susceptibility to comorbid depression in patients with CAD from a Northern Chinese population." (PMID 32547886, 2020). "Altered methylation of FKBP5 has previously been associated with depression and stress-dependent gene transcription." (PMID 32497228, 2020). "Systematic reviews and meta-analysis studies have proven that the SNPs of FKBP5 are associated with depression." (PMID 32547886, 2020). "Regarding FKBP5 and its association with pathophysiological alterations in the CNS in depressive disorders, further studies are needed." (PMID 32860562, 2020). "FKBP5 has been implicated in several mental disorders and stress-related conditions such as major depression, bipolar disorder, childhood trauma and posttraumatic stress disorder, aggressive and suicidal behavior." (PMID 30890970, 2019). "Factors associated with child abuse such as smoking, BMI, and depression all had main effects on FKBP5 methylation, including in dynamically responsive sites." (PMID 31122292, 2019). "In this study, patients with major depression carrying the T-allele carriers presented reduced FKBP5 mRNA induction and higher GR resistance when compared to the FKBP5 rs1360780 CC protective genotype." (PMID 31167373, 2019). "While previous findings quite consistently suggested the involvement of FKBP5 gene variants in depression risk and antidepressant treatment outcome, the role of FKBP5 gene expression was less clear." (PMID 30678080, 2019). "One specific example, the FKBP5 rs1360780 T-allele variant significantly increase susceptibility to depressive disorders, while the CC allelic variant has been shown to offer protection." (PMID 31167373, 2019).
depression (continued). "The stressors used in this study reduced Fkbp5 and Nr3c1 gene expressions in hippocampus associated with emotionality and reward pathways and reveals a role for CB2Rs in the mouse models of depression." (PMID 30042304, 2018). "This altered responsiveness to stress seems to predispose to psychiatric disorders; a number of studies linked FKBP5 polymorphisms with an increased susceptibility to major depression." (PMID 30533439, 2018). "A single nucleotide polymorphism of rs1360780 in the FKBP5 gene is associated with a predisposition to developing major depressive disorder (MDD)." (PMID 28198448, 2017). "Recently, a genetic variant within the gene encoding for FK506 binding protein 5 (FKBP5) was shown to be associated with major depression." (PMID 28096796, 2016). "Fkbp5 is highly associated with depression and other psychiatric disorders and is thought to reduce ligand sensitivity of the GR and be involved in stress response." (PMID 27701413, 2016). "More recent studies have determined that polymorphisms of the FKBP5 gene (a gene that plays a role in immune regulation) also modulate GRs, and have been associated with the development of depression." (PMID 27199779, 2016). "Given the important role of GR in regulating stress responses and the evidence for GR resistance in depression, polymorphisms within GR or FKBP5 genes have been studied as possible genetic factors for depression vulnerability." (PMID 26005424, 2015). "The FKBP5 gene is associated with depression, PTSD, anxiety and Alzheimer's disease (AD), but little is known about its role in aging." (PMID 25191701, 2014). "Our data demonstrate that FKBP5 deletion prevents the progressive age-associated increases in depression-like behavior and circulating CORT levels observed in wild-type mice." (PMID 25191701, 2014). "Functional genetic variants in FKBP5 have been described to alter stress hormone response regulation as well as the risk to suffer from depression and other psychiatry disorders when exposed to childhood trauma." (PMID 24741566, 2014). "As ELS and ELS × 5-HTT genotype interaction are associated with depression, we expected to find similar changes in the transcription of GR, MR, and FKBP5 as reported in clinical studies." (PMID 25352794, 2014). "In several genetic studies researchers linked FK506 binding protein 5 (Fkbp5) to stress-related diseases and phenotypes such as major depression, posttraumatic stress disorder, and recovery from psychosocial stress." (PMID 23733890, 2013). "These authors demonstrated that a risk variant for post-traumatic stress disorder and major depression in the FK506-binding protein 5 gene (FKBP5) is demethylated in several cell types in children exposed to trauma." (PMID 23820649, 2013). "Research in the last decade has shown that variation in the FKBP5 gene is associated with depression and several other mood and anxiety disorders." (PMID 21935478, 2011). "Analysis of FKBP5 genotypes and disease related variables produced only one positive association: in monopolar depression (n = 57) rs4713916AA was related to a short duration of disease (P = 0.011; without Bonferroni's correction)." (PMID 17081296, 2006). "Given these genetic and clinical findings, we tried to replicate the association of the FKBP5 gene locus with depression and disease-related variables in a case-control study of probands with similar ethnic background." (PMID 17081296, 2006). "Similarly, the overexpression of FKBP5 corresponded with lower neuron density in the hippocampus in mice exposed to early-life stress and increased susceptibility to depression-like behaviors." (PMID 40309821, 2025). "Another study further demonstrated that in key emotion-regulating brain regions, including the basolateral amygdala, PFC and hippocampus, both miR-124 and its target gene FKBP5 were significantly upregulated and closely associated with depression-like behavior." (PMID 40949123, 2025).